TNF (tumor necrosis factor)
Diseases named in the same sentence as TNF in open-access papers (continued):
Sharing a sentence is not in itself a finding about the gene and the disease.
colitis (continued). "However, lactic acid bacteria enriched in the colitis group showed a strong inverse correlation with colonic TNF-α, IL-1β,and IL-6 levels (p < 0.05)." (PMID 38528541, 2024). "TNF blockade was also shown to be associated with worse overall survival compared to steroid monotherapy in a cohort of melanoma patients, and among patients with ICI-colitis compared to vedolizumab treatment." (PMID 39737191, 2024). "In addition, VAWE recovers the mucosal barrier function of colitis, and protects against cell infection by down‐regulation of pro‐inflammatory cytokines (TNF‐α and IL‐6) and reduction of phagocytosis." (PMID 36596647, 2023). "al. showed that whole-body TNFα deficiency does not influence colitis development in the Winnie mouse model of ulcerative colitis." (PMID 37049400, 2023). "The specific deletion of Tnfaip3 only in epithelial cells (Tnfaip3ΔIEC) does not have a pathological phenotype but sensitize these mice to DSS‐induced colitis and TNF‐induced apoptosis: 24 h after injection of a sublethal TNF dose, LYZ‐containing PCs and expression of PC‐specific AMPs were reduced." (PMID 36573340, 2023). "Moreover, a deficiency of Atg16l1 in mouse spinal cord cells increased DSS-induced colitis and increased proinflammatory cytokine production (IL-1β, TNF-α)." (PMID 37554552, 2023). "Moreover, quercetin can affect some transcription factors, such as CCAAT/enhancer-binding protein β (C/EBP-β), to inhibit the production of downstream cytokines, including TNF-α and IL-6, in dendritic cells, thereby attenuating colitis in mouse models of IBD." (PMID 37107341, 2023). "We tested the genetic expression of inflammatory cytokines and found that the LCP diet reduced their expression in colitis, particularly in the P10 group, wherein levels of TNF-α, IL-1β, and IL-6 were diminished 3.0-, 3.2-, and 2.1-fold compared to the M group." (PMID 37761037, 2023). "Treatment of mice suffering from DSS or TNBS colitis with gallic acid, also found in tormentil, resulted in reduced colonic TNF-α and IFN-γ concentrations, which further supports our results of basal IFN-γ concentration in MLN taken from tormentil-treated C. jejuni-infected mice." (PMID 37896170, 2023). "Likewise, the downregulated Ezh2 enhanced the severity of a colitis mouse model through the facilitated nuclear factor kappa B (NF-κB) and tumor necrosis factor-alpha (TNF-α)." (PMID 36982437, 2023). "Oral NPs-PEG-FA/6-shogaol can downregulate the proinflammatory factors (TNF-α, IL-6, IL-1β and iNOS), upregulate the expression level of anti-inflammatory factors (Nrf-2 and HO-1), alleviate the colitis symptoms and accelerate the wound repair of DSS-induced colitis mice." (PMID 37033644, 2023). "In addition, the downregulation of COX-2 and TNF-α was also demonstrated in a mouse model of experimental colitis after treatment employing other flavonoids as those found in apple polyphenol extract." (PMID 37465689, 2023). "The European Crohn’s and Colitis Organisation (ECCO) guidelines state that the use of anti-TNFα mAb can be detrimental to patients undergoing cancer treatment and should be avoided for 2 years (5 years for patients with a high risk of recurrence) after cancer treatment." (PMID 36996146, 2023). "Ruminiclostridium-6 could contribute to the release of proinflammatory factors such as IL-6, IL-1β, TNF-α and IL-8 and deteriorate colitis." (PMID 37679821, 2023). "Furthermore, HG-9-91-01 treatment decreased colonic TNF-α and IL-12 levels and increased colonic IL-10 production in both colitis models." (PMID 36731029, 2023). "The results revealed that L. plantarum, COS, and the synbiotics alleviated the symptoms of mice colitis and inhibited the changes in short-chain fatty acids (SCFAs), tumor necrosis factor-α (TNF-α), interleukin (IL)-1β, IL-6, IL-10, and myeloperoxidase (MPO) caused by DSS." (PMID 37297494, 2023). "Unlike TNF-α and IL-6, high serum levels of IL-17 at baseline have been associated with severe colitis in patients on ipilimumab." (PMID 36900420, 2023).
colitis (continued). "According to the results, VK2 restored the colon lengths, improved the colonic histopathology, reduced the levels of proinflammatory cytokines (such as IL-1β, TNF-α, and IL-6), and boosted the level of the immunosuppressive cytokine IL-10 in the colon tissues of the colitis mice." (PMID 36769323, 2023). "To investigate the effect of BFO on the inflammatory responses of DSS‐induced colitis mice, we determined the mRNA expression levels colon‐related genes, including IL‐1β, IL‐6, TNF‐α, inducible nitric oxide synthase (iNOS), and cyclooxygenase 2 (COX‐2), by qPCR." (PMID 38018589, 2023). "On the other hand, inhibition of intestinal NHE8 expression could stimulate colitis-activated TNF-α expression, indicating the interplay of NHE8 and TNF-α." (PMID 38004229, 2023). "Finally, MAPKAPK2 is involved in gut inflammatory pathways and regulation of TNF gene expression, and its inhibition results in an improvement in animal models of colitis." (PMID 36378498, 2023). "Interestingly, upon colitis induction by DSS or C. rodentium infection, the loss of CLDN3 expression significantly exacerbated the expression of TNF-α and IL-6." (PMID 38010872, 2023). "Additionally, after the occurrence of colitis, proinflammatory cytokines, such as TNF-α, IL-6 and IL-1β, are secreted and accumulated in large quantities due to the excessive activation of immune cells." (PMID 36902109, 2023). "The authors hypothesized that the chitosan‐based gel reduced TNF‐α expression upon acquiring a single Chitosan‐CNP‐miRNA‐146a in dextran sodium sulfate (DSS)‐murine model of colitis/IBD." (PMID 38156400, 2023). "Similar to the situation in human disease, colitis could also be significantly attenuated by in vivo administration of anti-TNF mAbs." (PMID 37872166, 2023). "Oral administration of OA in a mice model of colitis significantly inhibited colon shortening and myeloperoxidase activity, displayed potent anti-inflammatory properties by reducing the activation of TNF-α, IL-1β, IL-17, NF-κB, and MAPK, and increasing the expression of IL-10." (PMID 36829984, 2023). "Regulated the colitis i gut microbiota, protected the mucosal barrier system, improved the antioxidant levels, decreased the weight loss and DAI, reduced the expression of TNF-α, up-regulated the expressions of IL-10." (PMID 37485519, 2023). "The colon’s TNF-α, IL-6, and IL-1β expressions were raised in experimental colitis." (PMID 37646040, 2023). "After seven days of treatments, our results indicated that oral vancomycin reduced the severity of DSS-induced colitis in mice, where weight gain and a decrease in IL-1 β and TNF-α levels were observed in the vancomycin group compared with other treatment groups." (PMID 37167242, 2023). "The findings from this study demonstrate that PNE improves colon inflammation in acetic acid‐induced colitis by increasing serum glutathione levels while inhibiting nitric oxide production and serum expression of the pro‐inflammatory cytokines, TNF‐α and IL‐1β." (PMID 37249276, 2023). "We found increased serum TNFα only at the early stage of colitis." (PMID 37810110, 2023). "Moreover, wheat-derived arabinoxylan suppressed TNFα production from type 1 helper T cells in this colitis model." (PMID 37049841, 2023). "Consistently with the data obtained in murine colitis, Ade/HA determined a significant decrease in the release of IL-1β, TNF-α, IL-6, MPO, and MDA accumulation in cytomix-stimulated tissues, and these effects were accompanied by a significant reduction in the expression of HYAL-1." (PMID 38203336, 2023). "In addition, in dextran sulfate sodium-induced colitis mice, Bifidobacterium not only downregulated levels of IL-6 and TNF-α, but also upregulated level of IL-10." (PMID 35918555, 2023). "In addition, the expression of the proinflammatory cytokine TNF-α was markedly increased in colon tissues of MKO colitis mice, compared with WT colitis mice." (PMID 36635421, 2023).
colitis (continued). "Other pro-inflammatory factors, such as TNF-α, are also important for the development of colitis." (PMID 36713833, 2023). "Additionally, in the mice models, the neutralization of TNFα improved the effectiveness of cancer immunotherapy, ameliorated immunotherapy-induced colitis, and overcame resistance to anti-PD-1 blockade in mouse melanoma." (PMID 36981837, 2023). "Similar to our findings, the serum level of IL-10 increased, and the plasma level of TNF-α was reduced after 14 days of TAX-treatment in a model of dextran sulfate sodium-induced colitis in mice (when compared to mice with colitis induced by dextran sulfate sodium)." (PMID 37628795, 2023). "Also, TNF- α was recently shown to have anti-inflammatory properties in a dextran sodium sulfate (DSS)–induced colitis model." (PMID 37187742, 2023). "Additionally, the brown seaweed extract reduced IL-6, IL-8, and TNF-α expressions in piglets with LPS-induced colitis, thereby inhibiting the pro-inflammatory factor response." (PMID 37233678, 2023). "Therefore, we assessed the effects of OPs on inflammation and oxidative stress in mice with colitis by measuring the levels of inflammatory markers (IL-6, IL-1β, TNF-α) and redox markers (MDA, SOD, T-AOC) in serum and colonic tissues." (PMID 38140314, 2023). "SIGNR3-deficient mice exhibited increased weight loss because of severe colitis symptoms compared to the wild-type littermates in a DSS-induced colitis model; SIGNR3-deficient mice showed increased inflammation in the colon with higher levels of TNF-α." (PMID 37191444, 2023). "Elevated production of inflammatory cytokines, such as TNF-α, IL-1β, and IL-6, could injure gut epithelia cells and exacerbate colitis." (PMID 37324477, 2023). "IBD patients show decreased rates of A. muciniphila and, in the mice models of colitis, the administration of A. muciniphila improves intestinal permeability, decreases colon inflammation and the expression of pro-inflammatory cytokines (TNF-α, IFN-γ)." (PMID 37515676, 2023). "Furthermore, previous studies revealed that oral gavage of live L. sakei alleviated symptoms and histopathology of colitis and reduced the expressions of pro-inflammatory cytokines (TNF-α, IL-1 and IL-6) in the colons of DSS-induced colitis animals." (PMID 36986118, 2023). "However, blockade of pro-inflammatory cytokines such as TNFα, holds promise as a method for reducing such adverse events, including checkpoint-induced colitis." (PMID 37461742, 2023). "Furthermore, in the acute model of colitis, TNF-⍺ concentrations were higher in the TNBS group compared to the EPO-treated groups, proving its pro-inflammatory effect." (PMID 37760938, 2023). "Hence, we explored the role of tumor necrosis factor α- (TNF-α-) pretreated MenSC-derived small EV (MenSCs-sEVTNF-α) in a mouse model of dextran sulfate sodium- (DSS-) induced colitis, expecting to find better therapeutic alterations." (PMID 36895784, 2023). "In a mice model of colitis, supplementation with penta-O-galloyl-β-D-glucose inhibited colon shortening and myeloperoxidase activity, reduced the activation of NF-κB and levels of IL-1β, TNF-α, and IL-6, but increased IL-10 levels." (PMID 36829984, 2023). "After 5 days of DSS administration, all mice developed severe colitis that could be prevented by treating them with unlabelled anti-α4β7 integrin or anti-TNFα mAb at therapeutic doses." (PMID 36986677, 2023). "Elevations of TNF-α production were observed the in colon and liver tissues of colitis rats." (PMID 36986118, 2023). "However, treatment with RG or fRG suppressed UCDF-induced myeloperoxidase, TNF-α, and IL-6 expression, and NF-κB+CD11c+ cell number, leading to the amelioration of colitis." (PMID 36926604, 2023). "Additionally, the effect of MDA resembles the anti-inflammatory effects induced by the A. adstringens extract when tested in a colitis model as it decreased the levels of cytokines such as TNFα and IFNγ and it also restricted tissue damage." (PMID 35209237, 2022).
colitis (continued). "Similarly, mice fed a high sugar diet have increased colonic IL-1β and TNF-α and develop more severe colitis in response to DSS treatment." (PMID 35450067, 2022). "TNF-α stimulated HT-29 cells are often used as an in vitro model of colon inflammation." (PMID 36557879, 2022). "irAEs refractory to glucocorticoids may require the administration of a mAb targeting TNF-α (i.e., infliximab) to treat certain irAEs such as colitis and pneumonitis." (PMID 35432346, 2022). "CD1d independent NK1.1+CD8+ T cells produced high levels of IFN-γ and TNFα, contributing to colitis pathogenesis, and suggested that DCs and macrophages might be responsible for increasing NK1.1+CD8+ T cells through IL-15." (PMID 35741032, 2022). "We isolated MLN and spleen from colitis mice and quantified the secretion of cytokine TNF-α." (PMID 35897919, 2022). "Similarly, the use of anti-IL17 monoclonal antibodies was found to exacerbate DSS-induced colitis in mice and increase the expression of pro-inflammatory markers such as TNF-α, IFN-γ, and IL-665." (PMID 36123355, 2022). "Activation of nuclear factor-κB (NF-κB) signaling was observed in the colonic epithelial cells in colitis patients, which could further stimulate the formation of proinflammatory cytokines or mediators such as IL-6, IL-17, TNF-α, and COX-2." (PMID 35269566, 2022). "Additionally, Fuc-S also successfully prevented colitis by inhibiting the production of TNF-α, IFN-γ, IL-6, and IL-17A in the colons of colitic mice." (PMID 36662189, 2022). "RJ also reduced CD3+, CD5+, CD8+ and CD45+ T cells; the secretion of pro-inflammatory cytokines IL-1β and TNF-α; the key inflammatory mediators (COX-2 and NF-κB); and injury caused by tumor necrosis factor in rat colitis induced by 2,4,6-trinitrobenzene sulfonic acid (TNBS)." (PMID 35631210, 2022). "Animal studies found that TNF blockade attenuated the development of colitis and colorectal cancer." (PMID 36618924, 2022). "Interestingly, supplementation with dietary arginine and glutamine significantly reduces colonic IL-17 and TNF-α in a DSS-induced colitis mice model." (PMID 35450067, 2022). "Thus, TNF-mediated control of IL-22BP production occurs both in murine and humanized TNF colitis models." (PMID 35383266, 2022). "Oxymatrine treatment has a significant regulatory effect on apoptosis by blocking the TLR-9/MyD88/NF-κB pathway associated with downstream TNF-α, IL-1β, and IL-6 protein expression levels, restoring TJ protein expression and attenuating TNBS-induced colitis symptoms." (PMID 35873579, 2022). "TNF-α is highly expressed in intestinal mucosa with CTLA-4-induced colitis." (PMID 36189293, 2022). "In a mouse (C57Bl/6) TNBS-induced colitis model, TNF-α was significantly increased in the smooth muscle layers of the colon (2 days after treatment) and TNBS-induced colonic motility dysfunction was attenuated in TNF-α deficient mice compared to wild-type mice." (PMID 35805922, 2022). "During colitis, TNF-α and IL-1β are secreted from monocytes and leukocytes." (PMID 36225573, 2022). "It was shown that Sinomenine significantly improved the inflammatory response of intestinal mucosa in colitis, inhibited the secretion of IL-1β and TNF-α, and improved the severity of colitis in mice by downregulating the level of miRNA-155 and other related inflammatory cytokines." (PMID 35873579, 2022). "Previous studies demonstrated that Uro-A reduced colon inflammation and improved intestinal barrier integrity in DSS-induced mouse models of colitis by reducing the cytokines interleukin 1 beta (IL-1β), interleukin 6 (IL-6), and tumor necrosis factor alpha (TNFα)." (PMID 35645801, 2022). "Thus, we next genetically depleted TNF in myeloid cells (M-TNF−/−× Rag1−/−; TNFf/f×Mlys-Cre×Rag1−/−) and in epithelial cells (EC-TNF−/−×Rag1−/−; TNFf/f×Vil-Cre×Rag1−/−) in Rag1−/− mice and induced colitis by transfer of naive T cells from WT mice." (PMID 35383266, 2022).
colitis (continued). "The authors found that in sedentary SD-fed mice, macroscopic and microscopic colitis was accompanied by a significant decrease in colonic blood flow and a significant increase in the colonic expression of tumor necrosis factor-alpha (TNF-α), IL-6, IL-1β, and leptin." (PMID 35456797, 2022). "A study in colitis mice revealed that feeding with the emmentaler (a particular cheese) fermented by Propionibacterium freudenreichii reduced IgA secretion in the small bowel, preventing the induction of TNFα, IFN-γ, and IL-17." (PMID 36235770, 2022). "Disturbance of intestinal immune regulation is an essential factor in the pathogenesis of IBD, in which proinflammatory cytokines TNF-α, IL-6, IL-1β and anti-inflammatory cytokine IL-10 are the key indicators reflecting the degree of inflammation in the model of colitis." (PMID 36615796, 2022). "In a colitis experimental model of colitis, vitexin significantly inhibited the TNF-α, IL-6, and IL-1β expression, suggesting that this compound may suppress the inflammatory response to improve colitis-induced liver damage." (PMID 35164352, 2022). "Indeed, single-cell RNA-Seq of colon tissues from patients who developed immunotherapy-induced colitis not only showed increased proinflammatory monocytes, but also showed increased expression of proinflammatory cytokines TNF-α and IL-1β." (PMID 36173679, 2022). "It has been confirmed that, compared with the negative group, Malassezia colonization can induce CARD9-S12N polymorphism and strongly enhance the release of cytokines such as IL-10 or tumor necrosis factor alpha (TNF-α) in either wild-type (WT) or Card9−/− colitis mice." (PMID 35309351, 2022). "Currently, the development of TNF-α–targeting drugs to manage colitis is a research hotspot." (PMID 36145120, 2022). "Peroral treatment with L. reuteri improved colitis severity clinically and morphologically and reduced the colonic levels of Tumor necrosis factor-α (TNF-α) (Tnf), Interleukin 1-β (Il1β), and nterferon-γ (Ifng), the crucial pro-inflammatory cytokines in colitis onset." (PMID 35320932, 2022). "In the same model, the mRNA expression and protein production of NFATc4 increased, while TNF-α and IL-1β expressions (both mRNA and protein) were downregulated by this treatment, thereby preventing weight loss caused by TNBS-induced colitis and improving macroscopic and microscopic scores." (PMID 36235004, 2022). "TNF-specific antibodies suppress chronic intestinal inflammation, and they may induce mucosal healing in colitis." (PMID 35897919, 2022). "A previous study showed that peanut shell extract (PSE) significantly alleviated inflammatory bowel disease (IBD) symptoms and reduced the inflammation in a rodent model of colitis as it markedly reduced the levels of pro-inflammatory cytokines as TNF-α and IL-6." (PMID 35326112, 2022). "Thus, next we aimed to evaluate the impact of TNFR2 signaling on anti-TNF induced recovery during established colitis." (PMID 35383266, 2022). "However, in this study, these two cytokines were not significantly changed, which differed from a previous report that L. acidophilus can down-regulate IL-1β and TNF-α to improve colitis." (PMID 36499169, 2022). "Additionally, our data demonstrate that TNF blockade during colitis results in decreased IL-22BP production by intestinal DCs, but not by T cells, suggesting different modes of regulation of IL-22BP expression by these two cell types." (PMID 35383266, 2022). "In a study examining murine colitis-associated colon cancer, fluoxetine was found to inhibit NF-κB activation and decrease TNF-α-mediated IκB kinase (IKK) and IκBα phosphorylation; thus suppressing dextran sulfate sodium (DSS)-induced colitis and colitis-associated tumorigenesis." (PMID 35565237, 2022). "In this study, we observed that HZJDD remarkably reduced the level of IL-6, CRP, and TNF-α in DSS-induced colitis rats, indicating that HZJDD could exert anti-inflammatory effects against DSS-induced in UC rats." (PMID 36313293, 2022).